CTLA4 (cytotoxic T-lymphocyte associated protein 4)
Diseases named in the same sentence as CTLA4 in open-access papers (continued):
Sharing a sentence is not in itself a finding about the gene and the disease.
tumor (continued). "GM-CSF producing vaccines have been tested along with CTLA-4 blockades in melanoma and lung cancer murine models, yielding promising results of tumor eradication." (PMID 33050151, 2020). "The CTLA-4 x OX40 bispecific antibody ATOR-1015 induces antitumor effects through tumour-directed immune activation." (PMID 32680511, 2020). "The loss of both host- and tumor-derived CD155 led to the greatest reduction in tumor growth and improved responses to anti-PD-1 or combined anti-PD-1 and anti-CTLA4 blockade." (PMID 33490104, 2020). "Exhausted CD8+ T cells continue to activate the expression of CTLA4 and other immune checkpoint receptors under the chronic stimulation of tumor antigens, which further promoting tumor invasion." (PMID 33117084, 2020). "Tumor volume was tracked as a function of standard intraperitoneal doses of single anti-PD-1 or anti-CTLA4 checkpoint inhibitors, as well as a control case." (PMID 32899865, 2020). "Different studies reported that combined with other immunotherapeutic agent, such as CTLA‐4 or PD‐1/PD‐L1 inhibitors, this objective response rates range from 10% to 57% among different tumour types." (PMID 32227579, 2020). "Combination treatment with antibodies against CTLA-4 and PD-1/PD-L1 was very potent in inducing tumor regression." (PMID 32226027, 2020). "The increased fraction of T cells expressing PD-1 or CTLA-4 in tumour compared to normal adjacent tissue was further mirrored in blood from CRC patients compared to healthy controls." (PMID 33228141, 2020). "By averaging z‐score expression levels per tumor, tumors with DDR mutation had lower expression levels of CTLA‐4, IFNG, TNF, FAS, and VTCN1, and higher expression levels of IL6, IL1B, and IL12A compared with the DDR wild‐type ones." (PMID 31991061, 2020). "Fully tolerized, self T cells—which share a very similar transcriptional profile to fixed, dysfunctional, tumor-specific T cells —are completely resistant to single target checkpoint blockade treatment as well as the combination of anti-CTLA-4 and anti-PD-1." (PMID 33339195, 2020). "Therapy based on immune checkpoint blockade (ICB) targets T cell inhibitory receptors such as programmed cell death-1 (PD-1) and cytotoxic T lymphocyte antigen-4 (CTLA-4), thus leading to activation of tumour-specific T cells." (PMID 32183246, 2020). "Several other strategies, such as treatment with an oncolytic vaccinia virus with deletion of the B18R gene deleted combined with CTLA-4 blockade, have also shown significant therapeutic responses in preclinical mouse tumor models." (PMID 33172438, 2020). "The provision of CTLA-4 blockade to the tumor fragments yielded a higher number of tumor-reactive T cells before and after rapid expansion." (PMID 32127601, 2020). "The results showed that when an A2AAR antagonist is combined with an anti-CTLA4 mAb, the therapeutic effects of inhibiting tumor growth and antitumor immune responses can be enhanced." (PMID 32911819, 2020). "Strikingly, disruption of dorsal MLVs alone, without affecting basal MLVs or nasal LVs, significantly reduced the efficacy of combined anti-PD-1/CTLA-4 checkpoint therapy in striatal tumor models." (PMID 32094452, 2020). "For instance, blockers of programmed cell death protein 1 (PD1) and cytotoxic T-lymphocyte-associated antigen 4 (CTLA4) indicate that there are broad and diverse opportunities for enhancing anti-tumor immunity by modulating the immune responses." (PMID 33193623, 2020). "Anti-CTLA-4 and anti-PD-L1 mAbs must bind activating FcγRs to exert potent anti-tumor activity by ADCC- or ADPC-mediated depletion of Tregs, or myeloid and tumor cells, respectively." (PMID 32917858, 2020). "Consistent with the survival data, tumor volume, as measured by MRI and GFP, as well as tumor weight significantly decreased in MLV-intact mice after anti-PD-1/CTLA-4 treatment." (PMID 32094452, 2020).
tumor (continued). "Significant Treg depletion was limited to tumor infiltrating lymphocytes in mice treated with Fc-effector anti-CTLA4, which have the highest density of CTLA4 expression." (PMID 33127658, 2020). "This combined treatment resulted in 71% complete and durable regression of 5-week tumors, a tumor-specific memory T cell response, and augmented response to systemic anti-CTLA-4 antibody checkpoint blockade." (PMID 32849544, 2020). "The anti-tumour effect of anti-CTLA-4 antibody is obtained by the inhibition of CTLA-4 on Treg and thus reversing the suppression of T cell activation." (PMID 31914969, 2020). "Targeting with CTLA-4, PD-1 or PD-L1 antibodies reverses the exhaustion of cytotoxic T lymphocytes thus leading to the elimination of tumor cells via the re-induction of the “natural” function of the T cell population." (PMID 32423420, 2020). "Aside from CTLA-4, minimizing the presence or activity of suppressive cells in the tumor microenvironment is an active area of research." (PMID 32467593, 2020). "The numbers of tumor-infiltrating CTLA-4+ cells were as follows: TCe parenchyma (range 0–15; median 1), TCe stroma (range 0–30; median 1), IF parenchyma (range 0–10; median 1), and IF stroma (range 0–24; median 2)." (PMID 32785290, 2020). "Flow cytometry and IHC confirmed the increase in tumor-infiltrating CD8a+ cells in XRT + anti-CTLA-4-treated mice." (PMID 32086762, 2020). "MicroRNA miR-138 was suggested to function as a tumour suppressor and has been shown to target CTLA-4 and programmed cell death 1 (PD-1) in CD4+T cells." (PMID 32054041, 2020). "Serine/threonine protein kinase CK2 inhibition blocked MDSC differentiation and substantially increased anti-tumor efficacy when combined with anti-CTLA-4 blockade in mice." (PMID 32443699, 2020). "Both CD44-targeted NIR-PIT and combination groups showed significantly smaller tumor volume than CTLA4 mAb group at 2, 5, 7, 10, 12, and 14 days after NIR-PIT (p < 0.05, Tukey–Kramer test)." (PMID 32937841, 2020). "Combination therapy with anti-CTLA-4 plus IL15/IL15Rα complexes enhanced tumour control compared with either monotherapy." (PMID 32680511, 2020). "As only one tissue expressed CTLA-4+ T cells in the tumor compartment, we noted a negligible intratumoral presence of CTLA-4+ T cells." (PMID 32635549, 2020). "Checkpoint inhibitor (CPI) therapy is based on blocking engagement of the inhibitory CTLA-4 and PD-1 receptors on tumor-specific Teff, with the primary effect of invigorating their antitumor function in the immunosuppressive tumor microenvironment." (PMID 32005826, 2020). "Our re-analysis of scRNAseq data of tumor-infiltrating T cells in NSCLC patients suggests that selective Treg depletion is achievable with anti-CTLA-4 antibodies." (PMID 31991588, 2020). "The antibody reduced the growth by 30% in SK-BR-3 and by 20% inLNCaP cells when incubated at a concentration of 100 nM for 72 h, suggesting that it directly inhibits the growth of CTLA4-positive tumor cells also independently from the immune system." (PMID 32024070, 2020). "Tumor-infiltrating Treg depletion by anti-CTLA-4 enhanced anti-PD-1 sensitivity to the previously resistant AT3 mouse mammary carcinoma." (PMID 32849557, 2020). "Tumor‐infiltrating lymphocytes express multiple immune checkpoint molecules (eg, PD‐1, CTLA‐4, TIM‐3, LAG‐3, and TIGIT)." (PMID 32077528, 2020). "In CNS metastatic diseases, ICI targeting PD1 (pembrolizumab, nivolumab) and CTLA4 (ipilimumab) have been shown to slow down progression or reduce tumour size." (PMID 32856125, 2020). "Tumor rejection by anti-CTLA-4/1MT therapy was associated with enhanced infiltration of functional CD8+ and CD4+ T-cells in the tumor." (PMID 33072086, 2020). "A combination of neutralization of microenvironmental acidosis with anti-CTLA4 or anti-PD1 immune check point antibody greatly improved the anti-tumor response of these therapies." (PMID 32707920, 2020).
tumor (continued). "Recently, it was demonstrated that both anti-PD1 and anti-CTLA-4 antibodies target a subset of tumor-infiltrating T cell populations, resulting in the expansion of exhausted-like CD8 T cells." (PMID 32655545, 2020). "In fact, EGFR activation contributes to the upregulation of PD‐1, PD‐L1, and CTLA‐4 expression levels as well as the decrease in T cell infiltration and reduces inflammation in the tumor microenvironment." (PMID 32997401, 2020). "The CTLA-4 and PD-1 immune checkpoint pathways downregulated T cell activation, thereby promoting immune tolerance and inhibiting anti-tumor immunity." (PMID 32635549, 2020). "Combination treatment with XRT and anti-CTLA-4 effectively inhibited tumor growth until day 22 post-therapy initiation (p = 0.0025) and increased the overall survival of mice compared to control (p = 0.0017)." (PMID 32086762, 2020). "Immunotherapy aims to block the interaction between PD-1 on T cells and its ligand PD-L1 on tumor cell or alternatively, blocking the interaction between CTLA-4 on T cells and its co-stimulatory receptors CD80, CD88 or B7 on antigen presenting cells." (PMID 32042336, 2020). "The addition of antibodies blocking PD-1 and CTLA-4 to shIDO-ST treatment results in increased tumor control compared to shIDO-ST with IgG or shScr-ST with ICB treatment." (PMID 33339195, 2020). "Cellular signals traveling through PD-1/PDL-1 and CTLA-4 axes work by smothering T cell activation, which in turn, prohibits tumor-directed adaptive immune response." (PMID 32258034, 2020). "The inhibition of CTLA-4 can prevent T-cell inhibition and enhance T-cell anti-tumor activity, making it an attractive target for antibody-based therapy." (PMID 33256070, 2020). "(C) Flow cytometry quantification of CD45+CTLA-4+ tumor infiltrating immune cells represented as a percentage of live cells." (PMID 31959281, 2020). "Thymocyte selection-associated high mobility group box gene (TOX) was reported as a positive regulator of PD1, TIM3, TIGIT, and CTLA4 expression in the tumor infiltrating CD8+ T cells, regulating CD8+ T cell exhaustion." (PMID 32793604, 2020). "Combination of IL36 and CTLA-4 mAbs resulted in even greater increases in CD45+ immune cells in tumor." (PMID 32351508, 2020). "CTLA-4 is also expressed in some cancer cells, but its activity in tumor cells is not completely understood." (PMID 32850353, 2020). "In the tumor microenvironment, the activity of T-cells is inhibited by CTLA-4 and PD-1/PD-L1, disabling the T-cells to destroy tumor cells." (PMID 32665852, 2020). "Overexpression of PD-1 and its ligand (PD‐L1) as well as CTLA‐4 in tumor and/or immune cells prevents T cell activation." (PMID 33298099, 2020). "Triple or quadruple treatment of AZA and ENT plus immunotherapy anti-PD-1 and anti-CTLA-4 exhibited highly effective tumor elimination." (PMID 32942545, 2020). "Probably, different ICs (e.g., PD-1, CTLA-4) and HLA-G influence each other as it has been reported, for instance, for TIM-3 expression on CD8+ tumor infiltrating lymphocytes that is closely associated with PD-1 expression." (PMID 32973812, 2020). "Antibodies against immune checkpoints (such as PD-1, CTLA-4) disrupt coinhibitory T cell signaling, thus reactivating the immune response against tumor cells." (PMID 33036244, 2020). "Immune checkpoint inhibitor (ICI) therapies, including anti-PD1, anti-PD-L1, and anti-CTLA-4 therapies, have played a role in enhancing the activities of effective T cells and inhibiting the immunosuppression in the tumor microenvironment." (PMID 32359357, 2020). "Chronic exposure to antigen in the tumor microenvironment leads to high expression of inhibitory receptors, such as PD-1, TIM-3, CTLA-4, and LAG-3, as well as a gradual loss of the ability to produce effector cytokines (IFN-γ, TNF-α, and IL-2) and proliferate." (PMID 32391270, 2020).
tumor (continued). "It has been established in several mouse tumor models that an anti-CTLA-4 antibody on the mIgG2a isotype induces anti-tumor responses via depletion of intratumoral regulatory T cells via FcγRIV engagement." (PMID 33117369, 2020). "Surprisingly, in order to reveal the role of NK cells in the anti-tumor response, Tregs needed to be controlled by anti-CTLA-4 therapy." (PMID 32117218, 2020). "Immune checkpoint blockade (ICB), targeting cytotoxic T-lymphocyte-associated protein 4 (CTLA-4) and the programmed cell death 1 (PD-1)/programmed death ligand 1 (PD-L1) axis, is an established standard of care in treating many tumours." (PMID 32546835, 2020). "The CTLA-4 antibody promotes the entry of anti-cancer immune cells into the surrounding tumor tissue and eliminates the immunosuppressive cells that promote cancer growth." (PMID 33585182, 2020). "In particular, treatment with anti-CTLA-4 and anti-PD-1 therapy in the low tumor burden state can lead to IFNγ dependent activation induced cell death of T cells." (PMID 32581235, 2020). "Nevertheless, PD1 and CTLA4 genes were more expressed in low tumor budding grade in both patients and xenografts." (PMID 32719800, 2020). "Perhaps CTLA-4 expression promotes tumor escape in the periphery (by inhibiting anti-tumor responses) but is incapable of inhibiting malignant lymphocyte proliferation through well-documented cell-intrinsic modes of immune suppression." (PMID 33384695, 2020). "Durvalumab (the anti–PD-L1 antibody) and tremelimumab (the anti–CTLA-4 antibody) can enhance T cells response to the tumor by blocking the immune checkpoint together, thus generating anti-tumor activity." (PMID 33469538, 2020). "These two lines of fundamental studies have inspired the development of the next generation of anti-CTLA-4 antibodies with enhanced ADCC activity or preferential activation in the tumor microenvironment." (PMID 31991588, 2020). "CTLA-4 also promotes immunosuppression in the tumor microenvironment by enhancing Treg activity and differentiation as well as interfering with the function of dendritic cells." (PMID 33374927, 2020). "Tumor cells evade destruction from the immune system by triggering immune checkpoint receptors, such as CTLA-4, PD-1, or PD-L1, that are expressed on T-cells and whose engagement inhibits T-lymphocyte function." (PMID 33333816, 2020). "By triggering antibody-dependent cellular cytotoxicity (ADCC)-mediated Treg depletion, CTLA-4 antagonists increase the T effector (Teff) cell proliferation and thus an immune response to the tumor." (PMID 32357515, 2020). "JX combined with anti-CTLA-4 and anti-PD-1 significantly decreased tumor burden and lung metastasis while increasing overall survival compared to any other group." (PMID 32937885, 2020). "There are currently extensive studies of tumor molecular biology and clinical trials with targeted molecular therapies, such as PD-1, PD-L1, and CTLA-4." (PMID 33080912, 2020). "The current approaches of numerous monoclonal antibodies (mAbs) targeting the immune checkpoints PD-1/PD-L1 and CTLA-4 are different as they reactivate a pre-existing anti-tumor immunity." (PMID 31953578, 2020). "So far, most of the treatments have focused on stimulating the adaptive immune system to kill tumor cells, including approaches targeting CTLA4, PD-1 or PD-L1." (PMID 32824974, 2020). "They inhibit the tumor immune response by producing high-affinity interleukin-2 (IL-2) receptor, CTLA-4, IL-10 and immunosuppressive cytokines such as transforming growth factor β (TGF-β)." (PMID 32916853, 2020). "PD-1 and CTLA-4 are the best known of the class of immune checkpoints, which abrogate T cell reactivity to cancers and are targeted by tumors to disable anti-tumor immunity." (PMID 32467593, 2020).
tumor (continued). "CD73 blockade led to increased infiltration and activation of CD8+ T cells and decreased regulatory T cells (Treg) in the tumor, associated with complete tumor regression during dual CD73 and CTLA-4 blockade in combination with irradiation." (PMID 32894202, 2020). "In the lymph node tissue, there was an opposing pattern, as the CTLA-4 and PD-1 expression levels were higher when the tumor sizes were 100 mm3 than in the other tumor growth stages (* P < 0.05)." (PMID 32805718, 2020). "Second, several groups, including ours, have reported that the therapeutic effect of anti-CTLA-4 antibodies requires ADCC activity that selectively depletes regulatory T cells in the tumor microenvironment." (PMID 31991588, 2020). "In both studies, blockade of CTLA-4 or PD-1 reduced tumor vascular density, improved vessel perfusion, and alleviated tumor tissue hypoxia, all of which were marks of the vascular normalization effect." (PMID 32983126, 2020). "For example, treatment with anti-PD-1/PD-L1 and anti-CTLA-4 immune checkpoint inhibitors reinvigorate dysfunctional TILs and augment their anti-tumor effects." (PMID 32117960, 2020). "Cytotoxic T-lymphocyte antigen-4 (CTLA-4) blockage weakens the function of Tregs, resulting in a stronger anti-tumor response." (PMID 33665156, 2020). "Pharmacological blockade of CD73 promotes anti-tumor immune responses and inhibits tumor metastasis, by reducing the accumulation of adenosine, and enhances the efficacy of anti-tumor agents, including anti-PD-1 or anti-CTLA-4 mAbs." (PMID 32160899, 2020). "A crucial tumor-intrinsic factor leading to ICB resistance is the low neoepitope load that generally leads to minimal immune reinvigoration with both CTLA-4 and PD-1/PD-L1 blockade." (PMID 31968651, 2020). "Under the combined inhibition of the inhibitory receptors CTLA-4 and PD-1, tumor-infiltrating T cell numbers increased, a change in the ratio of effector T cell to Tregs was induced, and effector T cell function was improved." (PMID 33162990, 2020). "In the anti-PD-1 combination setting, robust upregulation of tumor immune response genes was observed in all cohorts including mice treated with Fc-null or Fc-mutant pure CTLA4 antagonists." (PMID 33127658, 2020). "Given the tumor immunology, PD-1 mainly inhibits T cell activation in TM at later stages of tumor growth, whereas signaling via CTLA-4 regulates T cell activation in the early stage of T cell response in the lymph nodes (LNs)." (PMID 33519815, 2020). "In the local tumor microenvironment, CTLA-4 expression in Tregs upregulates IDO in DCs, which reciprocally promotes Treg activation." (PMID 33072086, 2020). "Combining LIGHT-VTP with anti-PD-1 and anti-CTLA-4 checkpoint inhibitors (dual checkpoint therapy) has also shown efficacy in combatting the tumor microenvironment." (PMID 32499782, 2020). "Luckily a solution exists, as CTLA-4-Ig treatment of tumor immunotherapy-induced myocarditis patients has a rescuing effect." (PMID 32296427, 2020). "Improving our knowledge on the activity of CTLA-4 on tumor cells will help to understand the potential effects of the receptor on the clinical response to immunotherapy." (PMID 32850353, 2020). "Checkpoint ligand-receptor pairs (e.g., tumor Treg CD80-Th17 cell CTLA4 and tumor Treg CD274-Th17 cell PDCD1) were identified." (PMID 33584715, 2020). "Second, the therapeutic immune checkpoint blockade of CTLA-4 or PDL1/PD1 reinvigorates exhausted tumor-infiltrating lymphocytes (TILs) and has anti-tumor effects in a subset of patients." (PMID 32040512, 2020). "In fact, despite the recent introduction of encouraging immunotherapies such as ipilimumab and pembrolizumab, that target CTLA-4 and PD-1 respectively, the majority of patients experience resistance and tumor progression." (PMID 32849585, 2020). "A2BR inhibitor also showed significant anti-tumor effects when combined with anti-PD-1 and anti-CTLA-4 mAbs." (PMID 32280302, 2020).